NUMB (NUMB endocytic adaptor protein)
Diseases named in the same sentence as NUMB in open-access papers (continued):
Sharing a sentence is not in itself a finding about the gene and the disease.
hepatocellular carcinoma (8 papers, 2014 to 2023). A malignant tumor that arises from hepatocytes. "Two splicing isoforms varying in the length of proline-rich region (PRR), PRRL and PRRS, were recently found to have opposite roles in hepatocellular carcinoma (HCC), suggesting that the alternative splicing of NUMB can serve as an important biomarker for HCC." (PMID 29220461, 2017). "Increased NUMB expression has also been reported in oral squamous cell carcinoma (OSCC), hepatocellular cancer (HCC) and endometrial cancer." (PMID 29721172, 2018). "We examined hepatocellular carcinoma (HCC) development in alcohol Western diet-fed hepatitis C virus NS5A Tg mice with hepatocyte-specific TBC1D15 deficiency or expression of non-phosphorylatable NUMB mutations." (PMID 32555153, 2020). "To establish the pathological relevance of SPTAN1, NUMB, MARK, WW45, and Hippo/MST1/2/YAP signals in patients with hepatocellular carcinoma (HCC), we examined 60 pairs of liver-derived tumorous and adjacent nontumorous tissues." (PMID 37843276, 2023).
melanoma (8 papers, 2014 to 2024). A malignant, usually aggressive tumor composed of atypical, neoplastic melanocytes. "The Kaplan-Meier survival curve showed that the expression of PLK1 and NUMB (isoforms 1-4) were inversely associated with survival of melanoma patients as high PLK1 with low NUMB showed significant decrease in OS compared to low PLK1 and high NUMB." (PMID 38184733, 2024). "In this study, we investigated the role of NUMB in the aggressive behavior of melanoma and its associated molec- ular mechanisms." (PMID 34883044, 2022). "NUMB KD caused morphological changes in the melanoma cells: they became spindle shaped with significantly elongated dendrites resembling mesenchymal cells." (PMID 34883044, 2022). "However, we found some inconsistent changes in EMT-related proteins in these three melanoma cell lines with WT NUMB and S413A/S413D mutations." (PMID 38184733, 2024). "Further, the knockdown of NUMB significantly increased the invasion potential of melanoma cells in vitro and in the lungs of a mouse model in vivo by modulating the NOTCH target gene CCNE7." (PMID 38184733, 2024). "Further, we analyzed protein levels of PLK1, NICD (NOTCH intracellular domain), and EMT-related markers in NUMB-modulated melanoma cells." (PMID 38184733, 2024). "We determined the expression of all four NUMB isoforms in melanoma by comparing TCGA data and GTEx data." (PMID 38184733, 2024). "It has previously been shown that miR‐146a‐5p down‐regulates NUMB leading to melanoma initiation and progression by activating the Notch signalling pathway." (PMID 37759347, 2023). "The metastatic melanoma cell lines WM1799 and WM3451 were transfected with lentiviral vectors encoding short hairpin RNAs targeting NUMB (shNUMBs) to downregulate NUMB expression." (PMID 34883044, 2022). "In contrast, two of the three examined primary melanoma cell lines demonstrated similar levels of NUMB expression to those of normal melanocytes." (PMID 34883044, 2022). "By mimicking Wnt stimulation through glycogen synthase kinase-3 inhibition, we increased NUMB expression in melanoma cells." (PMID 34883044, 2022). "To investigate the potential mechanism by which NUMB regulates invasion in melanoma, we performed quantitative real time-PCR to evaluate the expression of CCNE and MITF in WM1799 and WM3451." (PMID 34883044, 2022). "Analysis of The Cancer Genome Atlas melanoma datasets revealed that high NUMB expression in melanoma tissues correlates with improved patient survival." (PMID 34883044, 2022). "Although NUMB acts as a tumor suppressor in various human cancer types, little is known about its role in melanoma." (PMID 34883044, 2022). "NUMB is highly expressed in normal melanocytes and primary melanoma cells, whereas its expression is decreased in metastatic, aggressive melanoma cells." (PMID 34883044, 2022). "NUMB KD induced a significant increase in the invasion of melanoma spheroids into collagen matrices." (PMID 34883044, 2022). "This inhibitor upregulated the expression of NUMB protein in melanoma cell lines and activated b- catenin." (PMID 34883044, 2022). "NUMB knockdown significantly increased the invasion potential of melanoma cells in a three-dimensional collagen matrix in vitro and in the lungs of a mouse model in vivo; it also significantly upregulated the expression of the NOTCH target gene CCNE." (PMID 34883044, 2022). "The upregulation of the adaptor protein NUMB triggers melanocytic differentiation from multipotent skin stem cells, which share many properties with aggressive melanoma cells." (PMID 34883044, 2022). "Consis- tent with previous reports, we observed that NOTCH was barely expressed in WM1366 and WM3211 melanoma cells that have a high NUMB expression." (PMID 34883044, 2022). "In this study, we investigated the biological, mechanistic, and therapeutic role of NUMB in melanoma." (PMID 34883044, 2022). "In this study, we investigated the role of NUMB in melanoma progression and its regulatory mechanism." (PMID 34883044, 2022).
melanoma (continued). "First, to investigate the potential involvement of NUMB in melanoma progression, we analyzed melanoma RNA- sequencing data from The Cancer Genome Atlas, together with the patients’ clinical information." (PMID 34883044, 2022). "Together with our current findings, we suggest that NUMB suppresses invasion and metastasis in melanoma potentially through the NUMB–NOTCH–CCNE axis that regulates the cell cycle." (PMID 34883044, 2022). "Accordingly, a recent study shows that miR146a, upregulated by oncogenic BRAF, promotes the initiation and progression of melanoma cells through down-regulation of NUMB." (PMID 25986346, 2015). "Collectively, these results indicate that the ability of miR-146a to block NUMB expression and activate Notch signaling is necessary for miR-146a to promote melanoma initiation and progression." (PMID 24550252, 2014). "We confirmed NUMB as a direct target of miR-146a and showed that NUMB targeting and activation of Notch signaling was necessary for the ability of miR-146a to promote the initiation and progression of melanoma." (PMID 24550252, 2014). "We elected to focus on the NUMB mRNA because it encodes a repressor of NOTCH and several previous studies have shown that NOTCH functions as an oncogene in melanoma." (PMID 24550252, 2014). "In contrast, a recent study in human melanoma cells demonstrated that a targeted knockdown of NUMB expression disrupts its ability to interact with the serine/threonine polo-like kinase Plk1 thereby causing G2–M arrest and reducing cell growth." (PMID 24980814, 2014). "To confirm that NUMB downregulation is necessary for the ability of miR-146a to promote melanoma growth, we expressed either the miR-146a-resistant NUMB-MUT or NUMB-WT in SKMEL-28 cells expressing pre-miR-146a/G." (PMID 24550252, 2014). "Interestingly, ectopic expression of NUMB inhibited invasion, and the S413D phosphomimetic mutant rescued NUMB-inhibited invasion, which was consistent in all three melanoma cell lines tested." (PMID 38184733, 2024). "Interestingly, forced overexpression of NUMB inhibited invasion of melanoma cells significantly when compared to empty vector control, and the S413D phosphomimetic mutant significantly rescued NUMB-inhibited invasion when compared to NUMB overexpressing cells." (PMID 38184733, 2024). "Interestingly, using TCGA and GTEx databases, we found that NUMB isoforms -1, -2, and -3 were downregulated, while isoform-4 was upregulated in melanoma." (PMID 38184733, 2024). "As EMT has been considered a major determinant of melanoma metastasis, our study suggests a potential role of PLK1, NUMB, and NOTCH in the metastatic progression of melanoma that might be associated with poor survival of patients." (PMID 38184733, 2024). "Additionally, PLK1 and NUMB expressions were inversely associated with melanoma patient survival as high PLK1 with low NUMB (all isoforms 1-4) showed a significant decrease in patient survival compared to low PLK1 and high NUMB." (PMID 38184733, 2024). "The results suggested that NUMB overexpression, S413A, and S413D mutations did not affect cell proliferation of melanoma cells." (PMID 38184733, 2024). "However, further studies are required to delineate the role and functional significance of different NUMB isoforms in melanoma progression." (PMID 38184733, 2024). "Furthermore, data from The Cancer Genome Atlas (TCGA) also show a correlation between poor survival in melanoma patients and low NUMB expression levels." (PMID 37759347, 2023). "To explore whether NUMB af- fects melanoma invasion, we employed a three-dimensional spheroid model, which represents the complexity and het- erogeneity of tumors within tissues." (PMID 34883044, 2022). "In melanoma, NUMB is a target of microRNA-146a, which has an oncogenic role." (PMID 34883044, 2022). "Furthermore, a glycogen synthase kinase-3 inhibitor reduced the invasion of melanoma cells in a NUMB- dependent manner." (PMID 34883044, 2022).
melanoma (continued). "In this study, we sought to test whether NUMB expression could be increased in melanoma cells by pharmacologically acti- vating the canonical Wnt pathway." (PMID 34883044, 2022). "Our KD experiments suggested that NUMB negatively reg- ulates melanoma aggressive behavior." (PMID 34883044, 2022). "Because metastatic melanoma cells share embryonic and migratory phenotypes with neural crest–like precursors in the skin, we hypothesized that dysregulation of NUMB is involved not only in melanoma development but also in its progression." (PMID 34883044, 2022). "Furthermore, NUMB downregulation increased the expression of the NOTCH target gene CCNE, which is implicated in melanoma invasion and metastasis." (PMID 34883044, 2022). "To assess whether NUMB downregulation is directly involved in melanoma aggressive behavior, we performed NUMB knockdown (KD) experiments." (PMID 34883044, 2022). "To investigate the role of NUMB downregulation and activated Notch signaling in melanoma cell growth, we knocked down NUMB in SKMEL-28 cells and monitored cellular proliferation in liquid culture, anchorage-independent colony formation in soft-agar and tumor formation in mice." (PMID 24550252, 2014). "Furthermore, the target-specific inhibitors that can upregulate NUMB such as GSK-3 may exert useful therapeutic effects in aggressive melanomas." (PMID 34883044, 2022). "Next, we sought to investigate whether NUMB KD pro- motes the progression of melanoma in vivo." (PMID 34883044, 2022). "MiR-146a-5p acts targeting the NUMB gene, a repressor of NOTCH signaling, thus contributing to melanocytes transformation to primary melanoma." (PMID 38730639, 2024). "Thus, we hypothesized that PLK1 has a role in cellular invasion and metastasis by inducing EMT in melanoma cells and PLK1 phosphorylation of NUMB may be an important step in cellular reprogramming causing EMT via activation of the NOTCH pathway in melanoma cells." (PMID 38184733, 2024). "Overall, these results suggest the significance of PLK1, NUMB, and NOTCH signaling in melanoma progression and patient survival." (PMID 38184733, 2024). "Immunofluorescent staining showed that in the human melanoma cell lines WM1799, WM3451, and WM3211, NUMB was expressed mainly in the nucleus but also in the cytoplasm and cell membrane." (PMID 34883044, 2022). "Because MDM2 overexpression is an independent predictor of survival in patients with melanoma, it is possible that GSK-3 regulates NUMB expression in an MDM2-dependent manner." (PMID 34883044, 2022). "However, the exact role and significance of PLK1, NUMB, and NOTCH in melanoma remains to be determined." (PMID 38184733, 2024). "However, the exact role of PLK1, NUMB, and NOTCH signaling in epithelial-mesenchymal transition (EMT) in melanoma progression is unclear." (PMID 38184733, 2024). "Our findings support the therapeutic targeting of PLK1, NUMB, and NOTCH for melanoma management." (PMID 38184733, 2024). "Therefore, this study highlights the therapeutic significance of targeting PLK1, NUMB, and NOTCH in the clinical management of melanoma." (PMID 38184733, 2024). "Altogether, our study suggests that targeting PLK1, NUMB, and NOTCH may be a potential therapeutic strategy in inhibiting melanoma progression." (PMID 38184733, 2024). "Together, our results suggest that NUMB suppresses invasion and metastasis in mela- noma, potentially through its regulation of the NOTCH–CCNE axis and that the inhibitors that upregulate NUMB can exert therapeutic effects in melanoma." (PMID 34883044, 2022). "NUMB KD induced a significant increase in the invasion of melanoma spheroids into collagen matrices, although NUMB KD did not affect the proliferation over a 7-day period." (PMID 34883044, 2022).
melanoma (continued). "However, direct evidence supporting the involvement of PLK1 and NUMB in EMT process in melanoma is lacking." (PMID 38184733, 2024). "Moreover, NUMB is required for the stabilization and localization of the cell cycle regulator PLK1, suggesting that dysregulation of NUMB expression can contribute to melanoma development through mitotic errors." (PMID 34883044, 2022). "However, the role and functional significance of NUMB isoforms in melanoma is not clear." (PMID 38184733, 2024). "In addition, we conducted cell proliferation, migration and invasion assays utilizing WT NUMB overexpression, S413A-NUMB (non-phosphorylatable) and S413D-NUMB (phosphomimetic) clones of A375, WM115, and SK-MEL-2 melanoma cells." (PMID 38184733, 2024). "Additionally, as NUMB is a known NOTCH inhibitor, we analyzed the expression of NOTCH1 using TCGA melanoma patient data and found a non-significant decreasing trend in NOTCH1 expression with PLK1-low/NUMB-high expression when compared to PLK1-high/NUMB-low levels." (PMID 38184733, 2024).
colon cancer (6 papers, 2013 to 2025). "Depletion of SRPK2 impairs the invasion and migration of HCT116 colon cancer cells and reduces NUMB exon 9 inclusion." (PMID 39863103, 2025). "CD44 and NUMB alternative splicing (AS) isoforms have opposite functions in quasi-mesenchymal and epithelial colon cancer cells and their capacity to metastasize the liver." (PMID 36346211, 2022). "Last, we correlated the CD44 and NUMB isoforms expression in patient-derived colon cancers with functional signatures obtained by averaging the scaled expression levels for each of the hallmark sets." (PMID 36346211, 2022). "Gene and pathway correlation analyses of CD44 and NUMB isoforms in patient-derived colon cancers." (PMID 36346211, 2022). "Based on these results, we suggest that NUMB transcription might be differentially regulated through different binding capacities of other factors, along with RAC1, to the NUMB promoter region in breast or colon cancer cells." (PMID 30650643, 2019). "ESRP1 downregulation in EpCAMlo colon cancer cells affects alternative splicing (AS) of CD44 and NUMB among a broad spectrum of downstream target genes." (PMID 36346211, 2022). "We also considered the down regulation or loss of function of few tumor suppressor proteins such as GAS1, SUFU, NUMB, SNO etc., while simulating the colon cancer scenario, which in normal situation inhibited the GLI proteins." (PMID 23935937, 2013). "In colon cancer, KRT19 knockdown resulted in suppression of cancer via downregulation of Wnt/Notch signaling without altering NUMB transcription." (PMID 30650643, 2019).
glioblastoma (6 papers, 2010 to 2024). The most malignant astrocytic tumor (WHO grade IV). "Pairwise, we observed that NUMB expression inversely correlates with glioblastoma patients’ survival." (PMID 30890698, 2019). "This evidenced an inverse prognosis between NUMB expression and glioblastoma, indirectly confirming the role of NUMB in glioblastoma cell survival." (PMID 30890698, 2019). "Moreover, NUMB deletions and low NUMB expression levels have also been reported in pro‐neural glioblastomas." (PMID 33822486, 2021). "We tested whether in glioblastoma cells lines NUMB down-modulation induces p73 proteosomal degradation." (PMID 30890698, 2019). "Thus, the reduction of Bcl2 and NUMB decreases AKT phosphorylation and increases the apoptotic response in glioblastoma cell lines, highlighting the importance of ZIKV as a potential oncolytic therapy for glioblastoma treatment." (PMID 39347716, 2024). "Moreover, we observed that Zika infection reduces Bcl2 expression, which can be responsible for the apoptotic response, together with the reduction of NUMB, decreasing AKT phosphorylation in glioblastoma cell lines." (PMID 30890698, 2019). "To better dissect the NUMB function in glioblastoma, we overexpressed it in the U87MG cell line, negative for PTEN27." (PMID 30890698, 2019). "In addition, NUMB isoform 4, one of the predominant NUMB isoforms, decreases both NOTCH and EGFR expression in glioblastoma cells." (PMID 24302991, 2013).
lung adenocarcinoma (6 papers, 2015 to 2024). A carcinoma that arises from the lung and is characterized by the presence of malignant glandular epithelial cells. "In lung adenocarcinoma, high levels of NUMB can inhibit tumor growth, invasion, the Notch pathway, and the epithelial-mesenchymal transition." (PMID 38791918, 2024). "For instance, QKI has a splicing switch in lung adenocarcinoma that cannot be described in terms of simple events and which has better predictive power than well-known splicing changes in other genes, like NUMB." (PMID 25578962, 2015). "In a study about lung adenocarcinoma stem cells, miR-146 is referred to as the post-transcriptional regulation of NUMB, while one of its sponge TUSC-7, a strong suppressive lncRNA, could abolish the degradation toward to NUMB by inactivating NOTCH signaling." (PMID 32792861, 2020). "In another lung study, a mutation - caused by a T to A substitution and consequent valine (V) to glutamic acid (E) substitution within the second RRM (RRM2) of RBM10 - was reported in A549 lung adenocarcinoma cells, with consequences for NUMB alternative splicing." (PMID 25889998, 2015).